EGFR (epidermal growth factor receptor)
Diseases named in the same sentence as EGFR in open-access papers (continued):
Sharing a sentence is not in itself a finding about the gene and the disease.
tumor (continued). "Further study could be the mono/combinations of chemotherapy with gefitinib or inhibitors of the AKT pathway which should be tested in vitro in cell lines and in vivo in tumor xenografts with EGFR L858R mutations to determine whether these may be additive or synergistic." (PMID 23956990, 2013). "We found that the number of lymphatic vessels in EGFR-expressing tumors was fourfold higher than that observed in EGFR-deficient tumors, demonstrating that TGFα-EGFR signaling is an important cofactor for expansion of the tumor-associated lymphatic vascular network." (PMID 23986907, 2013). "Interestingly, several tumor-specific splice variants of EGFR have been identified." (PMID 24285959, 2013). "Finally, we evaluated whether the germline EGFR polyA repeat polymorphism or mutational status in tumor influence the risk of tumor recurrence in 64 patients with a localized form of CRC (stage I, II and III) followed for at least two years." (PMID 23565769, 2013). "However, patients may still have unknown EGFR mutation status at the time when first-line treatments decisions are made, due to limited high-quality tumor samples or insufficient testing facilities." (PMID 24236082, 2013). "Furthermore, EGFR TKIs have been recommended as first-line treatment for patients with advanced NSCLC that contain EGFR mutations due to the clinical benefits of these novel anti-tumor agents." (PMID 24376677, 2013). "Regarding the interaction of Resv with the EGFR system, the great majority of scientific sources available report studies on tumour cell lines, with Resv inhibiting the spontaneously increased, cancer-associated EGFR phosphorylation or synergizing with anti-cancer drugs-inhibitors of EGFR." (PMID 23527233, 2013). "In 8 tumor samples harboring two EGFR alleles of different size and in 10 non malignant tissues from patients with a heterozygous genotype, we could compare the EGFR allelic expression by calculating the mRNA ratios corresponding to the short / long allele." (PMID 23565769, 2013). "Furthermore, EGFR is known to regulate the expression of VEGF, and the resistance to tyrosine kinase inhibitors (TKIs) targeting EGFR may be partly associated with a rise in both host and tumor-derived VEGF." (PMID 23861835, 2013). "However, patients with activating EGFR mutations, for whom tumor progression is observed despite treatment based on TKIs, may acquire resistance to gefitinib or erlotinib." (PMID 23817662, 2013). "In conclusion, this study has provided epigenetic evidence that promoter hypermethylation of all three important GL-associated genes, DNMT1, MGMT and EGFR may play a role in GL progression and the inactivation of these genes is stable even as concerns tumour recurrence." (PMID 22264301, 2012). "Finally, we envision that by coupling our GEPR and miRNA predictor of response to EGFR inhibition a diagnostic may be possible that improves the accuracy of selecting patients with tumours that respond to EGFR inhibition." (PMID 22045191, 2012). "Furthermore, continuation therapy that incorporates cycling EGFR TKI treatment may suppress the outgrowth of aggressive drug resistant clones that can be associated with the clinical phenomenon of tumor flare upon discontinuation of EGFR TKI therapy." (PMID 22970367, 2012). "Although EGFR activating mutations in tumors have been predictive for clinical benefit to EGFR targeting agents (specifically TKIs), these somatic mutations are present in only the tumor and therefore cannot account for the positive association of skin rash and clinical benefit with these agents." (PMID 22997576, 2012). "According to this model, a discordance in mutation status between primary tumours and metastases may occur, and as a consequence the mutation status of the primary tumour might not be adequate to predict the response of metastases to anti-EGFR treatment." (PMID 21364579, 2011).
tumor (continued). "Larger prospective studies matching analysis of primary tumour and lymph node metastases are required to evaluate whether EGFR exon 19 deletions, or other mutations, are underrepresented in metastatic lymph nodes either at the time of diagnosis or in response to treatment." (PMID 21949883, 2011). "Our immunohistochemical analysis further suggests that the ALKBH3 expression profile of tumours may be a predictive factor for tumour recurrence of adenocarcinoma, in particular, and may also join EGFR mutational analysis as a marker for sensitivity to chemoradiation." (PMID 21285982, 2011). "The goal is to determine whether KRAS and EGFR mutation profile is stable during the metastatic progress and to investigate the clinical usefulness of mutational analyses in primary tumor versus in metastases for planning EGFR-targeted therapies for the treatment of patients with NSCLC." (PMID 21414214, 2011). "In vitro studies have revealed that tumor cells carrying non-T790 M mutations show a partial resistance to EGFR-TKI, but are much less resistant compared to cells with T790 M. These data suggest that an increased EGFR-TKI dose might circumvent the acquired resistance caused by non-T790 M mutations." (PMID 21194487, 2011). "Although the precise molecular mechanism of regulated CAIX shedding remains to be clarified, previous studies showed that dysregulation of HIF-1α could be caused by mutation in the von Hippel-Lindau (VHL) tumour suppressor gene or activation of the epidermal growth factor receptor (EGFR)." (PMID 20461082, 2010). "Additionally, certain tumor types may be more susceptible to signaling modulation by EGFR inhibition, perhaps because they are more reliant on the EGFR pathway for survival." (PMID 19657384, 2009). "EGFR activation is associated with proliferation,antiapoptosis, and metastatic spread, making this pathway a compelling target.Numerous large clinical trials have shown clinical evidence of anticanceractivity with these new agents resulting in improved tumor response andpatients' survival." (PMID 19424511, 2009). "In order to determine which tumor will be susceptible to anti-EGFR therapy, one may need to assess the level of phosphorylated EGFR as well as the level of phosphorylated downstream mediators, Akt, Erk1/2 and Stat3, the cytosolic end points to the three branches of the EGFR signaling pathway." (PMID 19765296, 2009). "In addition, targeting together mTOR and EGFR might cause a more profound effect on tumour growth control compared with a single agent." (PMID 18319715, 2008). "Indeed, in tumour progression EGFR upregulates VEGFR; thus, it is implicated in angiogenesis." (PMID 18522728, 2008). "The purpose of this study was to investigate the prognostic value of tumour-associated macrophages with a focus on the micro-anatomical localisation and to determine whether molecular changes in EGFR are associated with macrophage infiltration in patients with resected NSCLC." (PMID 18283317, 2008). "Sequencing of the cDNA derived from the pleural fluid of the progressing tumor confirmed the persistence of the initial L858R mutation in addition to a new T–C basepair change in exon 19, which results in a predicted amino acid change of leucine (L) to serine (S) at position 747 of EGFR." (PMID 17973572, 2007). "Interestingly, in the present study the highest expression levels of cytoplasmic HRGβ1 were found in patients with tumours that expressed high levels of membrane EGFR and increased activity of the EGFR-associated signalling elements, membrane erbB2, nuclear MAPK and nuclear AKT." (PMID 17686159, 2007). "Consequently, a variable part of the antiangiogenic activity of EGFR-targeting drugs could be caused by a dual effect: inhibition of proangiogenic factors such as VEGF produced by the tumour itself and a direct effect on the intra-tumour endothelial cells." (PMID 16940984, 2006).
tumor (continued). "In addition, regarding the growing understanding of the tumour–stroma interaction and the possible role of cancer-associated mesenchyme as a novel target for anticancer therapy, we also analysed the stroma of invasive breast adenocarcinomas for EGFR mutations." (PMID 15841079, 2005). "Our preclinical study found that the combination of the PLK1 inhibitor volasertib with the EGFR-TKI osimertinib induced complete tumor regression in EGFR-mutant NSCLC xenograft models, with sustained effects observed even after treatment cessation." (PMID 41539998, 2026). "When used in combination with EGFR-TKIs, they promoted cell apoptosis, inhibited cell proliferation in vitro, and induced tumor regression in animal models." (PMID 41539998, 2026). "Disruption of the amphiregulin-EGFR axis prevents early niche formation and abrogates tumour initiation." (PMID 42020743, 2026). "To investigate the clinical association of LAPTM4B and ATP1A1 with acquired EGFR-TKI resistance, we further analyzed paired tumor biopsies from six patients with EGFR-mutant NSCLC collected before treatment and after acquisition of EGFR-TKI resistance." (PMID 41362742, 2026). "SHP2 inhibition restored ICB sensitivity in EGFR-activated tumors, significantly reducing tumor burden while maintaining a favorable safety profile." (PMID 41538362, 2026). "Crucially, IMPREG-expressing tumors show enhanced sensitivity to EGFR inhibitors or anti-angiogenic therapies in specific tumor entities." (PMID 42103714, 2026). "Systemic treatment with the EGFR-MMP-MP1 fusion significantly reduced tumor size in MDA-MB-468 xenograft models, confirming in vivo efficacy against cancer cells and acceptable systemic toxicity." (PMID 41920242, 2026). "Adenosine detection assays revealed that the majority of adenosine was produced by tumor cells, particularly in EGFR‐mutant tumors, whereas fibroblasts and Tregs contributed minimally." (PMID 41144813, 2026). "The EGFR signalling pathway has been reported to participate in therapeutic resistance, maintenance of stem‐like tumour cells and immunological regulation in BC." (PMID 41555955, 2026). "The aptamer enabled selective recognition and binding to EGFR-mutant cells, thereby enhancing tumor-selective intracellular delivery of erlotinib." (PMID 41560835, 2026). "Silencing of SNHG10 decreases cell survival, proliferation, clonogenicity, EMT tumor growth through the EGFR/AKT/ERK/mTOR axis, and restores the expression of miR-150-5p, which eventually downregulates VEGF-A." (PMID 41916965, 2026). "In Iceland, EGFR testing was initiated in 2005, and in 2016, multigene targeted panel became standard for tumor testing." (PMID 41954526, 2026). "MTX-241F increased the number of immunopeptides in DMG but reduced them in GBM, indicating a tumor-specific change in the immunopeptidome following EGFR/PI3K inhibition." (PMID 41643293, 2026). "Our findings identify MFN2 as a critical suppressor of tumor immune evasion through the EGFR/STAT3-PD-L1 signaling pathway." (PMID 41896539, 2026). "Here, we present a spatially stratified single-cell atlas of IDH-wildtype GBM to dissect the impact of EGFR amplification on tumor architecture." (PMID 42087893, 2026).
tumor (continued). "The research demonstrated that tumors with amplified EGFR displayed heightened phosphorylation of downstream signaling proteins, including STAT3 and ERK1/2, associated with greater tumor cell proliferation and survival." (PMID 41562920, 2026). "Pharmacologic blockade of TGF-α with Fepixnebart, a first-in-class ligand-neutralizing antibody targeting TGF-α and previously not tested in oncologic indications, significantly inhibited early lymph metastasis of EGFR+ tumor cells." (PMID 41932901, 2026). "Nanoparticles functionalized with antibodies or peptides specific to EGFR/EGFRvIII enhance tumor targeting, cellular uptake, and the delivery of chemotherapeutics or imaging agents." (PMID 41574218, 2026). "Tyrosine kinase receptors, such as the epidermal growth factor receptor (EGFR), are often aberrantly activated by gene mutation and drive tumor growth." (PMID 41691060, 2026). "Existing research suggests that the immunosuppressive tumor microenvironment (TME) in EGFR‐mutant NSCLC plays a pivotal role in immune evasion." (PMID 41144813, 2026). "Previous preclinical studies on immune remodeling mechanisms in EGFR-mutant LUAD have mostly leveraged models that exogenously express EGFR mutants in EGFR wild-type murine tumor cell lines, primarily (such as) LLC and MC38 47-50." (PMID 41356800, 2026). "PGG dose-dependently inhibited the ANP32E/KDM3B/EGFR axis in vitro and suppressed tumor growth in vivo." (PMID 41980942, 2026). "Following IHC confirmation of DCBLD1 overexpression in two cases (Case 1: EGFR WT; Case 2: EGFR Mut, exon 19 deletion), tumor tissues were used to establish both PDO and PDX models." (PMID 41522352, 2026). "As a result, DCs exposed to CM from EGFR‐mutant tumor cells displayed diminished capacity to prime human CD8+ T cells, as shown their significant reduced proliferation and cytokine secretion." (PMID 41144813, 2026). "There are limited preclinical models available to mimic immune dynamics and tumor microenvironment of EGFR-mutant LUAD." (PMID 41356800, 2026). "Analysis of clinical NSCLC tumor specimens confirmed elevated LAPTM4B protein expression in EGFR-mutant (exon 19 deletion) samples, relative to EGFR wild-type samples." (PMID 41362742, 2026). "For example, PTEN and CASP8 act as tumor suppressors, whereas STAT3, MYC, EGFR, and TGFB1 are canonical oncogenic drivers implicated in cell cycle progression, stemness, and therapy resistance, particularly in triple-negative BC." (PMID 41596512, 2026). "The EGF-Exo was effectively internalized by tumor cell lines in a manner dependent on EGFR expression levels, and exhibited enhanced accumulation in xenograft A549 tumors relative to the heart, with minimal cardiac accumulation." (PMID 41593600, 2026). "These B7-H3-CAR-T-EGFR-BsTe cells exerted dual functionality: direct B7-H3-dependent cytotoxicity and recruitment of unmodified T cells via secreted EGFR-BsTe to eliminate EGFR-expressing tumor cells." (PMID 42301527, 2026). "This alteration drives tumor growth and contributes to resistance to certain therapies, particularly EGFR inhibitors." (PMID 40491286, 2026). "Consistent with the tumor responses, EGFR‐19del LLC tumors contain significantly lower numbers of CD11c+MHC‐II+ DCs, which express reduced levels of CD80 and CD86, than the WT tumors." (PMID 41144813, 2026). "ex., typical tumor drivers BCAN, APOE, and EGFR or genes associated to neuronal function like EGR1, FOS, and MARCKS)." (PMID 40188875, 2026). "Recent studies demonstrate that HHLA2 promotes tumor progression by enhancing EGFR/MAPK/ERK signaling, thereby supporting proliferation, invasion, and epithelial-mesenchymal transition." (PMID 42266686, 2026). "This nanodrug significantly improves the therapeutic efficacy of PD‐1 blockade, leading to robust tumor growth inhibition and prolonged survival of mice in EGFR‐mutant NSCLC models." (PMID 41144813, 2026).
tumor (continued). "For the aggressive, fast-proliferating, immune-infiltrated Cluster #2 tumours with basal/squamous differentiation, cytotoxic agents and EGFR/ERBB- and MEK/ERK-targeting therapies were proposed." (PMID 41804750, 2026). "Clinical responses were not explained by conventional clinicopathological factors or EGFR expression on tumor cells." (PMID 42039183, 2026). "Analysis of clinical databases revealed that PLK1 mRNA expression is more markedly elevated in tumor tissues than in adjacent normal tissues from EGFR-mutant NSCLC patients." (PMID 41539998, 2026). "Amivantamab is an EGFR-MET-bispecific antibody that not only inhibits EGFR and MET pathways but also stimulates immunologic reaction against tumour cells harbouring EGFR-activating mutations." (PMID 41590374, 2026). "In the successfully constructed EGFR‐19del tumor cells, their phosphorylation levels of EGFR were notably elevated compared to the EGFR‐WT cells (p = 0.0015), indicating an enhanced activation of the EGFR signaling." (PMID 41144813, 2026). "CDK12 knockdown combined with sorafenib suppresses tumor growth by over 70% and reduces expression of EGFR, c-MET, and DDR1, key drivers of HCC progression." (PMID 41491919, 2026). "BC patients exhibiting EGFR overexpression typically present with lower tumour differentiation grades, higher clinical stages and higher rates of lymph node metastasis." (PMID 41555955, 2026). "Conversely, in EGFR-dependent tumors, PTP1B suppresses tumor growth by dephosphorylating EGFR upon EGF stimulation." (PMID 41522352, 2026). "Using the CoaLPD technology, we successfully degraded HER2 and EGFR in cancer cells and in tumor-bearing mice, showcasing its potential use as an anticancer treatment." (PMID 41738074, 2026). "More importantly, the combination of F127ZIF‐8AB680 with PD‐1 blockade demonstrates a synergistic effect, restoring immune function and significantly reducing tumor burden in preclinical models of EGFR‐mutant NSCLC." (PMID 41144813, 2026). "Protein levels for HBEGF, human tumor cell markers (vimentin), EGFR and astroglial differentiation markers (GFAP, Meteorin) were determined by Western Blot in all treatment groups." (PMID 41181988, 2026). "We targeted T and NK92 ACDVs to cancer cells possessing the xenoantigen, N-glycolyl neuraminic acid GM3 ganglioside, using the 14f7hT antibody or the tumour antigen, epidermal growth factor receptor, using the nimotuzumab antibody." (PMID 41618610, 2026). "In light of our findings and the published literature, we postulated that the activation of STAT3 serves as a “self-protective” mechanism employed by tumor cells to counteract inhibition of the EGFR/MEK/ERK pathway." (PMID 41539998, 2026). "Together, these findings demonstrate that the NK cell–derived AREG protects tumor cells from IFN‐γ–induced apoptosis in an EGFR–dependent manner." (PMID 41082397, 2026). "Here, we show that the mAb inhibits the shedding of EGFR ligands and EGFR phosphorylation in cancer cell lines, thus explaining its anti-tumor effects." (PMID 41977126, 2026). "Remarkably, the EGFR mutant tumor cells products reduced the expression of HLA‐DR, CD86, and CD80 on DCs compared to WT cells (all p < 0.05), although they did not significantly alter the phagocytic ability of DCs." (PMID 41144813, 2026). "The emergence of a KRAS mutation in the metastatic site explained resistance to anti-EGFR therapy and highlighted the importance of reassessing tumor genetics during disease progression." (PMID 42130526, 2026). "Studies in mouse models have validated that KRASG12D inhibitors, KRASG12V inhibitors, and the Pan-RAS inhibitor exhibit synergistic anti-tumor effects when combined with EGFR monoclonal antibodies." (PMID 41362725, 2026).